XRCC1 (X-ray repair cross complementing 1)
Diseases named in the same sentence as XRCC1 in open-access papers (continued):
Sharing a sentence is not in itself a finding about the gene and the disease.
cancer (continued). "Three coding polymorphisms (Arg399Gln, Arg194Trp, and Arg280His) were most extensively studied in the XRCC1 gene, and it was widely accepted that functional variants in this gene may play a crucial role in the development of cancer because of the alteration of base excision repair functions." (PMID 23383237, 2013). "Therefore, sequence variation in the XRCC1 gene is suggested to alter cancer’s susceptibility." (PMID 24086310, 2013). "Polymorphisms in XRCC1 are associated with cancer and this may be exploitable by ATR inhibition." (PMID 21730979, 2011). "Among these, LUSC showed particularly strong statistical significance, suggesting a potential role of XRCC1 in modulating TMB in this cancer type." (PMID 38217545, 2024). "Particularly, the Arg194Trp and Arg399Gln variants of XRCC1, the Arg188His variant of XRCC2, and the Thr241Met variant of XRCC3 have been studied for their associations with various types of cancer." (PMID 38983993, 2024). "In our analysis, we utilized receiver operating characteristic (ROC) curves to assess the predictive ability of XRCC1 expression levels in distinguishing between cancer and normal tissue across multiple cancer types." (PMID 38217545, 2024). "In the context of tumorigenesis, XRCC1 manifests distinct expression profiles in different cancer tissues and serves as a valuable biological marker for tumors." (PMID 38217545, 2024). "The study conducted an analysis of XRCC1 expression in relation to immune subtypes and molecular subtypes of human cancer using the subtype module of the TISIDB database." (PMID 38217545, 2024). "Remarkably, our findings identified XRCC1 as a novel prognostic and immunological biomarker, holding promise as a molecular target in numerous cancer types, with particular significance in LGGs." (PMID 38217545, 2024). "We separated the cancer cases into low-expression and high-expression groups based on the gene expression levels of XRCC1." (PMID 38217545, 2024). "Our first pan-cancer analysis of XRCC1 revealed a statistical correlation between XRCC1 expression and clinical prognosis, DNA methylation, protein phosphorylation, TMB, MSI, immune cell infiltration, and immune checkpoints." (PMID 38217545, 2024). "We explored the relativity between XRCC1 gene expression levels and the survival prognosis across cancer types with the assistance of GEO and TCGA datasets." (PMID 38217545, 2024). "Our analysis aimed to examine XRCC1 expression levels across diverse cancer types and elucidate its prognostic implications." (PMID 38217545, 2024). "Overall, XRCC1 emerges as a promising biomarker for cancer diagnosis, prognosis, and immunological assessment, particularly in the context of LGG." (PMID 38217545, 2024). "We conducted an analysis of XRCC1 genomic alterations in pan-cancer using the cBioPortal (TCGA, The Pan-Cancer Atlas) database." (PMID 38217545, 2024). "Overall, our study highlights the potential of XRCC1 as a prognostic and immunological pan-cancer biomarker, thereby offering a novel target for tumor immunotherapy." (PMID 38217545, 2024). "The results demonstrated significant correlations between XRCC1 expression and the abundance of infiltrating immune cells in various cancer types." (PMID 38217545, 2024). "The results indicated that XRCC1 gene expression levels were significantly correlated with TMB status in several cancer types, including SARC, LUSC, UCS, and DLBC." (PMID 38217545, 2024).
cancer (continued). "Alterations in XRCC1, involved in the BER pathway crucial for repairing SSBs induced by ionizing radiation, have been associated with increased risk for several cancers." (PMID 40191738, 2024). "In summary, we found that the gene expression level of XRCC1 was mainly relevant to the poor survival prognosis of patients with various cancer types." (PMID 38217545, 2024). "Cancer cell viability, proliferation, migration, and invasion were promoted by overexpressed circFLNA, XRCC1, and CYP1A1 but inhibited by miR-486-3p mimic and circFLNA knockdown." (PMID 33500536, 2022). "Both X-ray repair cross-complementing group 1 (XRCC1) and 8-oxoguanine DNA glycosylase 1 (OGG1) are components of the BER pathway, and polymorphisms in XRCC1 and OGG1 are clinically important in various human cancers." (PMID 36497451, 2022). "There has been an accumulating body of work suggesting that XRCC1 influences cancer progression and cisplatin-resistance." (PMID 35293383, 2022). "XRCC1-mediated MMEJ repair was found to result in the mutagenic chromosomal translocations leading to cancer." (PMID 35293383, 2022). "The remaining shared hits in the 5 cancer cell lines included X-Ray Repair Cross Complementing 1 (XRCC1), PARP1, Replication Protein A1 (RPA1) and DNA ligase 3 (LIG3)." (PMID 36386669, 2022). "DNA-damaging agents are commonly used in cancer therapy and the altered expression of XRCC1 has been found to modulate responses in numerous cancers." (PMID 35457130, 2022). "The aim of this work was to study the immunocytochemical localization of XRCC1 and γH2AX foci induced by femtosecond laser radiation in human cancer A549 cells (lung adenocarcinoma)." (PMID 34279367, 2021). "More importantly, the transcriptional regulation of XRCC1 is poorly understood in general, and even less is known about the drivers of dysregulation in cancer." (PMID 34067421, 2021). "The Cancer Genome Atlas (TCGA) database was searched to further verify the relationship between XRCC1 expression and radiotherapy-related cancer prognosis." (PMID 34094945, 2021). "To further explore the prognostic value of XRCC1 expression in cancer patients who received radiotherapy, we retrieved expression data for radiotherapy-related cancer prognosis in all cancer types from TCGA data set." (PMID 34094945, 2021). "XRCC1, a single-strand break repair factor, has been reported to play essential roles in various cancers." (PMID 34486486, 2021). "The aim of this work was to study the immunocytochemical localization of DNA repair protein foci (XRCC1 and γH2AX) induced by tightly focused femtosecond laser radiation in human cancer A549 cells." (PMID 34279367, 2021). "Genetic variants in BER genes, including XRCC1 and MUTYH, have been associated with the risk of developing several types of cancer including BC." (PMID 33942220, 2021). "A small molecule inhibitor of LIG1 (L82) was tested for synthetic lethality application in XRCC1, BRCA2 or ATM deficient cancer cells." (PMID 34373746, 2021). "XRCC1 overexpression is correlated with increased aggressive features and reduced cancer-specific survival in ovarian tumor samples." (PMID 34067421, 2021). "XRCC1 and PARP1 deficient cancer cells have been demonstrated to show greater sensitivity to cisplatin." (PMID 33076245, 2020). "Similar to XRCC1 and XRCC2, XRCC3 has been researched widely in the correlation between gene polymorphisms and the risk of cancer." (PMID 32258128, 2020). "XRCC1 functions as a scaffold protein in the BER and its aberrant expression is associated with carcinogenesis of multiply human malignant tumors." (PMID 32426369, 2020).
cancer (continued). "Previous studies have demonstrated that XRCC1 plays a role in regulating cell biological features such as proliferation, migration, invasion, and drug resistance in several human cancer cell lines." (PMID 32426369, 2020). "Like APE2, PCNA, BRCA2 and XRCC1 were also significantly upregulated in all cancer types except prostate." (PMID 32111912, 2020). "As a DNA repair gene, XRCC1 is involved in tumorigenesis, progression, and poor prognosis of many human cancer types." (PMID 32426369, 2020). "We have shown that APE2 expression is positively correlated with the expression of PCNA, APE1, PARP1, XRCC1, Chk1, and Chk2 across all six cancer types analyzed in this work." (PMID 32111912, 2020). "XRCC1 was diffused in control cancer cells, the resolution was incomplete and XRCC1 foci were observed in digoxin-treated cells." (PMID 32180730, 2020). "Across all 6 cancer types, APE2 expression was significantly positively correlated with the expression of PCNA, APE1, PARP1 and XRCC1 yet expression ranges varied per cancer type and gene-gene pair." (PMID 32111912, 2020). "Associations between XRCC1, XRCC3, and ERCC2 gene polymorphism and prognosis have been investigated in several cancers." (PMID 31281357, 2019). "Western blot showed BBR down‐regulated XRCC1 expressions, and the rescued XRCC1 recovered the resistance of cancer cells to BBR." (PMID 31338966, 2019). "The frequencies of the XRCC1 R194 genotype are 38.7% in the cancer group and 49.0% in the control group, while those of XRCC1 R399 genotype are 15.3% and 19.0%, respectively." (PMID 31247975, 2019). "In conclusion, we found that several types of cancer show a profile with a lower ALDH2 and a higher XRCC1 expression that is linked to a poor prognosis." (PMID 30088263, 2018). "Co-culturing XRCC1 KD fibroblasts and H1299 cells in Boyden chamber assays stimulated the invasive capacity of the cancer cells." (PMID 29568385, 2018). "Globally at the median value, we found that ALDH2 is downregulated by more than two-fold and XRCC1 is upregulated by more than two-fold across all cancer types." (PMID 30088263, 2018). "Lastly, midostaurin completely prevented the stimulatory ability of XRCC1 KD fibroblasts towards cancer cells, when delivered to XRCC1 KD/H1299 co-cultured spheroids." (PMID 29568385, 2018). "Specifically, IRF9 and XRCC1 were highly expressed in the tumors from PsP patients and both of them are involved in cancer suppression and prevention." (PMID 27421136, 2016). "In this study, to elucidate the mechanism of DNA repair in oleandrin induced anti-tumor effect, we measured expression of DNA damage repair proteins RAD51 and XRCC1 in oleandrin-treated cancer cells." (PMID 27449097, 2016). "XRCC1 with high expression can not only prevent cancer prior to the radiation therapy but also promote the resistance to TMZ." (PMID 27421136, 2016). "XRCC1 loss would provide a strategy to exploit a specific PDA vulnerability, and further increase the tumor selectivity of ß-lap in these cancers by the mechanism above." (PMID 26602448, 2015). "A recent review of the literature found an overall modification of the effect of smoking by XRCC1 across several cancer types." (PMID 26271249, 2015). "Sociodemographic characteristics, cigarette smoking status, cancer stage, tumor grade, XRCC1 genotypes, and urinary 8-OHdG level of urolethial carcinoma (UC) cases and healthy, non-UC controls." (PMID 25938407, 2015). "XRCC1 was overexpressed in normal cells and in cisplatin-resistant cancer cells when challenged with cisplatin." (PMID 25476899, 2014). "Our findings suggest a novel and specific role of XRCC1 in the repair of DNA damage and survival of cancer cells following 5-azadC treatment." (PMID 25074383, 2014). "For instance, only two studies have reported the combined effect of XRCC1 Arg194Trp and PARP-1 Val762Ala genotypes on the risk of cancer." (PMID 24853559, 2014).
cancer (continued). "Our data clearly indicate that XRCC1 deficiency perturbs the BER pathway and sensitizes cancer cells to 5-azadC treatment." (PMID 25074383, 2014). "These variations were shown to be able to alter the function of XRCC1, diminish repair kinetics and lead to altered protein efficiency, eventually inducing the development of cancer." (PMID 25202399, 2014). "The functions of the BER pathway in the process of DNA repair require the use of the XRCC1 protein, which has a significant role in genome integrity and stability, and in human cancer pathogenesis and progression." (PMID 25202399, 2014). "Second, our meta-analysis explores and analyzes the sources of heterogeneity between studies about XRCC1 Arg399Gln in cancer." (PMID 24205095, 2013). "However, the exact mechanism for association between different tumor sites and XRCC1 Arg399Gln polymorphism was not clear, carcinogenetic mechanism may differ by different tumor sites and the XRCC1 genetic variants may exert varying effects in different cancers." (PMID 24205095, 2013). "Therefore, the XRCC1 Arg194Trp polymorphism may exert different effects on different cancers." (PMID 23226774, 2012). "Here we present the current knowledge about the role of XRCC1 and its variants in BER and human disease/cancer." (PMID 23247283, 2012). "BRCA2 N372H (rs144848), XRCC1 R399Q (rs25487), and OGG1 S326C (rs1052133) are three SNPs in DNA repair genes consistently associated with cancer risk, supported by thirty studies." (PMID 18547414, 2008). "XRCC1 has been shown to have a large number of SNPs, several of which are being increasingly studied in cancer epidemiology investigations and age-related diseases, in part because of their relative high frequency in the population." (PMID 17242676, 2007). "In this case the low positive rate of XRCC1 mRNA in the carcinoma group (27%) was significantly lower than that for the common pathological changes group (77%; p < 0.01)." (PMID 17450239, 2007). "In stage T3/T4 patients, cancer-specific survival was plotted for XRCC1 genotypes, combined XPD and XRCC1 genotypes, and the number of variant alleles in DNA repair genes (respectively)." (PMID 16880786, 2006). "The relationship between the combined XPD and XRCC1 genotypes and cancer-specific survival was stronger in stage T3/T4 patients." (PMID 16880786, 2006). "We found a significant relationship between combined XPD and XRCC1 genotypes and cancer-specific survival in muscle-invasive bladder cancer patients treated with CRT." (PMID 16880786, 2006). "The protective effect of the codon 194 Trp allele observed in our study is consistent with several studies of cancers and XRCC1 genotype." (PMID 16796765, 2006). "Because of its important role in the repair capacity of BER, variability in XRCC1 expression has been examined extensively in relation to various age-related diseases, including cancer." (PMID 16457697, 2005). "PARG and NAMPT inhibitors could therefore represent therapeutic opportunities for cancers displaying PARP1 hyperactivity, including XRCC1-deficient cancers." (PMID 41459749, 2025). "This variation raises the possibility that other genetic modifiers, such as variations in DNA repair genes like XRCC1 and XPD, could increase the risk of cancer in people with CHEK2." (PMID 40507526, 2025). "Furthermore, we explored the potential connections between XRCC1 expression and DNA methylation patterns, tumor mutational load (TMB), microsatellite instability (MSI), and immune infiltration levels in various cancer contexts." (PMID 38217545, 2024). "Moreover, we explored the expression of XRCC1 in a broader range of cancer tissues using the Cancer Cell Line Encyclopedia (CCLE) database, which provided cell line expression matrices for various tumor types." (PMID 38217545, 2024).
cancer (continued). "Furthermore, the analysis of PFS and DSS across multiple cancer types further supports the relevance of XRCC1 gene expression levels to the survival prognosis of cancer patients." (PMID 38217545, 2024). "That is, increased expression of XRCC1 corresponds to a poor prognosis in most cancers." (PMID 38217545, 2024). "Therefore, we systematically analyzed XRCC1 concerning expression, prognostic types, immune invasion, methylation, phosphorylation, and molecular typing in various cancers." (PMID 38217545, 2024). "Therefore, further prospective studies are needed to explore the relationship between XRCC1 expression and immune infiltration in cancer patient populations." (PMID 38217545, 2024). "Additionally, positive associations were observed between XRCC1 expression and common lymphoid progenitor infiltration, as well as T cell CD4+ Th1 and Th2 cell infiltration, across various cancer types." (PMID 38217545, 2024). "XRCC1 (X-ray repair cross-complementing protein 1) expression and its single nucleotide polymorphism XRCC1 rs25487 (G>A) may be related to radiotherapy-related cancer prognosis or radiation-induced side effects." (PMID 34094945, 2021). "Based on these similarities, we speculated that the expression patterns of genes expressed during spermiogenesis may also be similar to those in cancer cells, namely, the expression patterns of tumour–testis-associated genes, such as PRAMEL1, Xrcc1, and TSLC1." (PMID 33466297, 2021). "XRCC1 is a DNA repair gene that plays a crucial role in maintaining genomic integrity and stability and in the pathogenesis and carcinogenesis of various type of cancer." (PMID 33868991, 2021). "XRCC1 is thus an endogenous PARP1 anti-trapper that safeguards genome integrity during BER by preventing PARP1 from impeding this essential DNA repair process in a manner reminiscent of anti-cancer PARP inhibitors." (PMID 34102106, 2021). "However, increased DNA repair in cancer cells is a main cause of DDP resistance 6; and XRCC1 is a vital factor in single strand break repair (SSB) and base excision repair (BER) which causes the development of DDP resistance in various cancers." (PMID 33753987, 2021). "Thus, we propose that activated STAT3 regulates XRCC1 under stress and growth conditions, but constitutive activation in cancers results in dysregulation of XRCC1 and subsequently BER and SSBR." (PMID 34067421, 2021). "Moreover, XRCC1 affects the effectiveness of chemotherapy and the role of XRCC1 in chemosensitivity varies in different types of cancer." (PMID 32426369, 2020). "Therefore, we conclude that BBR interferes with XRCC1‐mediated base excision repair to sensitize cancer cells to chemotherapeutic drugs." (PMID 31338966, 2019). "However, one of the mentioned genes, namely XRCC1, was taken under study in the same cancer (n = 118) but with respect to the other polymorphic site." (PMID 31468363, 2019). "Variation in XRCC1 expression may modulate cancer sensitivity, clinical treatment efficiency, and prognosis." (PMID 31281357, 2019). "We found the rescued XRCC1 recovered the resistance of cancer cells to BBR." (PMID 31338966, 2019). "Thus, we assessed the ability of XRCC1 KD fibroblasts to support growth and motility of cancer cells." (PMID 29568385, 2018). "In addition, we found that Mithramycin A, a XRCC1 expression inhibitor, efficiently kills cancer cells expressing low levels of ALDH2." (PMID 30088263, 2018). "Our data suggest that XRCC1 expression levels in tumour stroma may be a crucial determinant for cancer progression and for the genesis of a tumour-promoting microenvironment." (PMID 29568385, 2018).